CAT (catalase)
Diseases named in the same sentence as CAT in open-access papers (continued):
Sharing a sentence is not in itself a finding about the gene and the disease.
tumor (continued). "Therefore, the CAT loaded in DDRi@CAT‐PD‐M1Exos could effectively relieve tumor hypoxia." (PMID 35715382, 2022). "MnO2 displayed the CAT-mimic catalytic activity that decomposed H2O2 to form O2 and alleviate tumor hypoxia." (PMID 36873299, 2022). "The encapsulated CAT within nanoparticles decomposed H2O2 in tumor tissue to generate O2 and thus relieved tumor hypoxia, which greatly improved the RT effect in a mouse tumor model." (PMID 35119544, 2022). "The excessive generation of ROS leads to an imbalance between reactive species and antioxidants, resulting in a decrease of antioxidant enzymes like SOD, CAT, and GSH, and eventually in tumor growth." (PMID 35661799, 2022). "We also found much lower expression levels of ECA-binding-membrane CAT and P4HB in HCC tumor tissues than adjacent non-tumor tissues from three HCC patients." (PMID 35392238, 2022). "Nine genes were upregulated in tumor tissues, while the PRKCD, RPS6KA1, CAT, and VEGFC genes were downregulated." (PMID 36254009, 2022). "Interestingly, the authors confirmed that such a synergistic strategy could sensitize radiation therapy to tumor cells by the production of oxygen through the biological activity of the catalase, and by the deregulation of HDACs through the application of the HDACi." (PMID 35163980, 2022). "The enzyme activity of CAT loaded inside of the liposome was preserved, and it decomposed endogenous H2O2 in tumor to mitigate hypoxia." (PMID 35624636, 2022). "After HA receptor-mediated endocytosis of cancer cells, CAT@HA-HMME NPs can be cleaved by the HAase, resulting in the disassembly process in tumor to release HA-HMME molecules and CAT." (PMID 35387175, 2022). "After HA receptor-mediated endocytosis of cancer cells, CAT@HA-HMME NPs can be cleaved by endogenous hyaluronidase, resulting in the on-demand disassembly in tumor to release HA-HMME molecules and CAT." (PMID 35387175, 2022). "These glucose oxidase (GOx) and catalase (CAT) nanoreactors can significantly increase antitumor efficacy and display efficient tumor accumulation." (PMID 36338748, 2022). "Nanozymes with CAT-mimic activity can transfer H2O2 to O2 and supply enough O2 to reverse hypoxia tumor microenvironment." (PMID 36531332, 2022). "Tumor hypoxia can be substantially relieved by the conversion of endogenous H2O2 into molecular oxygen; however, the enzyme CAT, which promotes this conversion, is also poorly present in the TME." (PMID 35740402, 2022). "The 131I-labeled catalase (131I-Cat) was mixed in ALG and injected into the tumor site, resulting in the decomposition of hydrogen peroxide in the tumor, which improved the oxygenation status of the tumor." (PMID 34842684, 2021). "Whereas, mice bearing tumor treated with AT or Gl recorded elevation in tumor Malondialdehyde (MDA) accompanied by a decline in GSH, SOD and CAT activities in comparison to the Ehrlich group." (PMID 33906301, 2021). "Cin showed a protective role against TeA induced tumours in the stomach, and thus elevated the activity of SOD, CAT and LPO in prophylaxis groups." (PMID 34593834, 2021). "CAT, an enzyme to rapidly decompose H2O2 into H2O and O2, as shown in equation, but the expression of tumor cells is significantly down regulated when compared to normal tissues." (PMID 34277702, 2021). "The production of 1O2 was remarkably enhanced as compared with the control group of water, H2O2, and M-BCD in a tumor simulation TME, so the key component for catalase capacity was Pt NPs." (PMID 34277702, 2021). "In the current study, mice bearing tumor treated with AT and /or Gl recorded high elevation in tumor MDA whereas high reduction of GSH, SOD and CAT activities in comparison to the Ehrlich group." (PMID 33906301, 2021). "For the oxygen-generating strategies, it mainly uses oxygen generators such as catalase (CAT) or CAT-mimics (nanozymes) to decompose the over-expressed hydrogen peroxide (H2O2) to produce oxygen at the tumor cells." (PMID 34277702, 2021).
tumor (continued). "To better understand the increased ROS-mediated damages in tumor tissues, we assessed the protein expression of three major antioxidant proteins, super oxide dismutase (SOD), catalase, and thioredoxin (TXN)." (PMID 33799792, 2021). "Catalase (CAT) is a catalytic enzyme with a high turnover number to decompose H2O2 into O2 and thus can be employed to relieve tumor hypoxia." (PMID 33954158, 2021). "RBAC was also shown to enhance the activity of the endogenous antioxidant scavenging enzymes, which include superoxide dismutase (SOD), glutathione peroxidase (GPx), catalase (CAT) and glutathione-S-transferase (GST), in blood, liver, and tumor tissue." (PMID 33925340, 2021). "For example, PB nanozymes (PB NZs) have exhibited catalase (CAT)-like activity and therefore catalyzed the breakdown of hydrogen peroxide (H2O2), producing oxygen in tumor microenvironments for photodynamic therapy." (PMID 34488789, 2021). "Treatment with Candesartan either alone, or in combination with 5-FU decreased tumor size in the mouse model, and also increased the level of oxidative markers MDA and reduced CAT, SOD, and thiols." (PMID 34121975, 2021). "On the other hand, the antioxidant enzyme activity showed that the efficiency of metal complex 1′ against P815 tumor cells was via the rise in the SOD activity and inhibition of CAT enzyme activity." (PMID 35494785, 2021). "Concomitant high NQO1 and low CAT mRNA levels (high NQO1:CAT ratios (p < 0.0001) in HCC tumor tissue offer an ideal target for NQO1 bioactivatable drugs." (PMID 34676172, 2021). "As Nrf2, also FOXM1 activated the antioxidant proteins SOD2 and CAT in MPM cells towards HMC, so counteracting oxidative stress in tumor cells." (PMID 33799965, 2021). "The expression levels of AR, CAT, CYP3A4, ESR1 and SLC10A1 were markedly upregulated in primary tumour tissues compared with normal tissues." (PMID 34717619, 2021). "The data revealed that solid tumor tissue of mice bearing tumor showed an increase in MDA while a decrease in GSH, SOD and CAT was recorded as compared to the normal group." (PMID 33906301, 2021). "After cellular uptake by cells, TPP ligand directed the nanoplatform to mitochondria, and CAT decomposed endogenous H2O2 to oxygen within tumor cells, alleviating tumor hypoxia." (PMID 34490227, 2021). "(QD@P)R nanoparticles, assisted by the anti-tumor drug PEITC, utilized catalase enzyme of RBC membrane to relieve tumor hypoxia, thereby further enhancing the SDT effect on the tumor under the guidance of fluorescence imaging." (PMID 31903156, 2020). "Indeed, as happened in our study, elevated expression of ROS-scavenging enzymes, such as superoxide dismutase, catalase, and glutathione reductase, has been observed in healthy cells as compared to tumor cells, which might contribute to cellular defense against CAP-originated reactive species." (PMID 32438553, 2020). "The catalase-entrapped nanocapsules exhibited efficient passive retention in tumors after intravenous injection, which could significantly overcome tumor hypoxia by triggering the decomposition of endogenous tumor H2O2 into oxygen, achieving a remarkable antitumor therapeutic effect." (PMID 32641993, 2020). "The activity of NOX (p < 0.01) and XO (p = 0.01), as well as SOD (p < 0.0001), CAT (p < 0.0001) and TAC level (p < 0.01) were significantly higher in tumour tissue than in normal colon mucosa." (PMID 32575703, 2020). "Afterwards, more and more researchers tried to use the combination of catalase and MOF to design nanoscale drugs to alleviate the hypoxia of tumors and to carry out tumor treatment, thus achieving good antitumor effect." (PMID 33343807, 2020). "These authors have also found significant increases in levels of antioxidant enzymes, superoxide dismutase, glutathione peroxidase and catalase, following TPT treatment, indicating oxidative stress was induced in MCF-7 tumor cells by TPT." (PMID 32765594, 2020).
tumor (continued). "We also assessed the content of antioxidant enzymes and observed increased activity of CAT and SOD in tumour tissue compared to normal tissue." (PMID 32575703, 2020). "By using mature liposome carriers, they deliver CAT and exogenous H2O2 to the tumor in turn, thereby promoting tumor oxidation and providing a good idea and platform for alleviating tumor hypoxia." (PMID 33343807, 2020). "These CMS nanoparticles also acted as the catalase‐mimicking nanoenzymes to convert endogenous H2O2 into O2, which was further used by the loaded GOx for converting tumor‐uptaken glucose into H2O2 for starvation therapy." (PMID 33173728, 2020). "Once the nanomaterial targeted into tumor cells, the abundant H2O2 in tumor cells would enter into the interior of nanomaterial and be catalyzed by catalase to produce O2." (PMID 35492191, 2020). "In their study, the Pt NPs acted as a CAT-mimic, catalyzing over-expressed H2O2 in a tumor microenvironment (TME) into O2." (PMID 33330357, 2020). "A multifunctional immunoliposomes named CAT@aPDL1-SSLs promoted the delivery and accumulation of anti-PDL1 antibodies in tumor tissues to activate the infiltration of CD8+ T cells at the tumor site with low systemic toxicity." (PMID 33408716, 2020). "Normal and tumor cells have various protective mechanisms, including induction of cellular antioxidant enzymes (e.g., SOD, catalase, and various peroxidases) as well as DNA repair enzymes for oxidative DNA damage (e.g., glycosylases)." (PMID 32765594, 2020). "In order to overcome the hypoxic conditions often found in the tumor site, a H2O2-activatable catalase was incorporated in the NPs." (PMID 33202648, 2020). "Examples include the preference of H2O2 in attacking the amino acids near heme group and the requirement of interactions between short-lived species like singlet oxygen with catalase and NOX1 that are often present on tumor cell surface." (PMID 33202842, 2020). "After 14 days after the treatment, the tumour volumes for PBS, Ce6, chitosan + Ce6, catalase + Ce6 and C&C-Ce6 NPs were respectively 1.87±0.14 cm3, 1.04±0.09 cm3, 0.99±0.15 cm3, 0.96±0.12 cm3 and 0.52±0.11 cm3, in good agreement with in vitro results." (PMID 31671658, 2019). "At higher doses of CAP, the effect on control tumor cells (siCo) remained dependent on NOX1, but cells with the knockdown of NOX1 (siNOX1) and subsequent downmodulation of catalase, also showed apoptosis induction." (PMID 31578342, 2019). "It is interesting to note that catalase is able to convert around 5 million H2O2 molecules per minute and catalase is explored nowadays to overcome tumour relief." (PMID 31671658, 2019). "Very recently, the tumor oxygenation by delivering exogenous H2O2 and the subsequent catalase-triggered H2O2 decomposition/oxygen generation has been proposed to offer a more effective approach for tumor oxygenation." (PMID 34138044, 2019). "Despite the prime role of hydrogen peroxide in cytotoxicity as seen with catalase controls, this suggests plasma-derived oxidants other than H2O2 to play in role in oxidation and cytotoxicity in tumor cells." (PMID 30679720, 2019). "Marsdenia tenacissima inhibits tumor growth via the modulation of VEGF, MMP-2, MMP-9, GSH-Px, SOD, CAT, and MDA." (PMID 31341493, 2019). "Catalase inactivation then seemed to allow H2O2 and ONOO− that are continuously generated by the tumor cells, to survive long enough to generate substantial amounts of secondary 1O2 through the reaction between H2O2 and ONOO−55." (PMID 31578342, 2019). "Washing of the tumor cells immediately after CAP treatment and further incubation in fresh medium resulted in a negligible catalase inactivation." (PMID 31578342, 2019). "Catalase has a specific catalytic behaviour and is able to decompose endogenous H2O2 to produce O2 bubbles in the tumour tissue." (PMID 31671658, 2019). "Protein and total RNA were then extracted from each tumour and used to assess the expression levels of HIF-1α, FoxO1, Sesn3, MnSOD and catalase." (PMID 31905813, 2019).
tumor (continued). "Under external NIR, the nanoreactor released catalase and decomposed the abundant H2O2 in tumor cells into oxygen for 1O2 production, which enhanced PDT effect." (PMID 31508270, 2019). "We then examined the tumor growth and luciferase expression in C57BL/6 mice receiving HDI with the plasmids pKT2/CLP-AKT-OVA-HBc-HBs-LUC, pT/Caggs-NRASV12, and pCMV(CAT)T7-SB100 and found two different patterns of tumor growth in the injected mice." (PMID 30526672, 2018). "Consistent with the in vitro observations, the tumor xenografts showed reduced activation of key mediators of the PI3K/PKBα and ERK pathways when catalase was present." (PMID 28102840, 2017). "Western blot analysis identified the tumor stage-dependent elevation of NRF expression and antioxidant enzyme (MnSOD, catalase, and GPx) activity." (PMID 28915605, 2017). "Based on their functional changes, the heme-containing enzymes, nitric oxide synthase (NOS) and catalase (CAT), as the targets of artemisinin were clarified from bacteria and tumor cells." (PMID 29089893, 2017). "Changes in ratios of antioxidant proteins (e.g., SOD/catalase and SOD/GPX1) translate into differential intracellular concentrations of H2O2, and they vary with cancer stage and between metastatic and primary tumor cells." (PMID 28744456, 2017). "After selective uptake of the nanoparticles by αvβ3 integrin‐rich tumor cells, H2O2 permeated into the core and was catalyzed by catalase to generate molecular O2, leading to the dissociation of the nanoparticles and release of MB." (PMID 28105390, 2017). "The antioxidant enzymes, such as SOD, CAT, GPx GR and GST, were reduced in tumor-bearing rats (p < 0.05)." (PMID 27187346, 2016). "Whereas in tumor cells, the activity of SOD and CAT is weaker than in normal cells, leading to the accumulation of ·O2−, which promotes cell proliferation and increases the sensitivity of these cells to H2O2." (PMID 26330167, 2015). "In tumor cell culture, MEC increased catalase, metallothionein and superoxide dismutase expression in accordance with the antioxidant tests." (PMID 24879583, 2014). "Thus, low catalase expression in tumors compared to non-tumor tissues could serve as a valuable predictor of poor survival of patients with advanced HCC, and enhancement of catalase expression in tumors could be a useful therapeutic strategy for the treatment of HCC." (PMID 25361011, 2014). "In view of the interesting divergences in the liver and tumour activity of the U. tomentosa BHE extract and its BuOH fraction, we measured the protein expression of catalase and SOD-1 in these tissues by means of Western blot." (PMID 23408945, 2013). "The activities of the antioxidant enzymes CAT and SOD in the liver and kidney of S180 tumor-bearing mice were assayed." (PMID 23731702, 2013). "In our studies, overexpression of catalase and antioxidant (Ebselen) prevented 4-OH-E2-induced anchorage independent growth of MCF-10A cells as well as xenograft tumor growth." (PMID 23437041, 2013). "We have shown that the cumulative induction of endogenous antioxidant enzymes (i.e., catalase, total SOD and MnSOD) is efficient in reducing tumor incidence and multiplicity." (PMID 22007296, 2012). "Second, the PB-Au component possessed both catalase (CAT)-like and glutathione oxidase (GSHOD)-like activities, which not only decomposed endogenous H2O2 to relieve hypoxia but also depleted GSH to weaken the tumor's antioxidant defenses." (PMID 41510161, 2026). "This phenomenon was due to the initial burst release of CAT from UP, which could lead to the rapid consumption of substrates such as H2O2 at the tumor site." (PMID 41355957, 2026). "In summary, a simple strategy for synthesizing Janus Zn-Mo dual-atomic sites was developed to optimize the adsorption/desorption of O-containing reaction intermediates during POD, CAT and OXD-like enzyme processes, thereby improving the efficacy of tumor catalytic therapy." (PMID 41492652, 2026).
tumor (continued). "In another study, intake of Lactococcus lactis, a CAT-producing bacterium, prevented DMH-induced CRC in mice as evidenced by increased CAT activity, which led to significantly lower levels of H2O2, limited inflammatory colonic damage, and tumor shrinkage in comparison with the untreated animals." (PMID 40869174, 2025). "For instance, the engineered tumor-targeting probiotic Escherichia coli Nissle 1917 significantly promotes the secretion of catalase within the tumor microenvironment, catalyzing the conversion of H2O2 produced by tumor cells into O2, and enhancing ROS production under hypoxic conditions." (PMID 40618373, 2025). "Furthermore, these studies have evidenced that HTX can modulate the activity of key antioxidant enzymes such as SOD, CAT and glutathione peroxidase (GPX), as well as increase reduced GSH levels, contributing to a less favorable environment for tumor growth." (PMID 40864821, 2025). "Similarly, a biodegradable tumor-targeting nanocarrier designed to release Fenton-like Cu2+/Cu enhances GSH depletion, inhibits catalase (CAT) activity, and promotes the generation of hydroxyl radicals (•OH), ultimately leading to tumor apoptosis." (PMID 40703657, 2025). "Herein, CAE pre- and post-treatments significantly decreased MDA levels, while enhancing the activities of ROS scavenging enzymes, including SOD, CAT, GPx, GRD, and elevated TAC in tumor tissues, and enhanced the expression of the antioxidant enzyme Gpx4 at the mRNA levels." (PMID 40898252, 2025). "Studies measuring the activities of antioxidant enzymes, specifically superoxide dismutase (SOD) and catalase (CAT), in tumor tissue after RA administration have shown a significant reduction in their activity, which was associated with a decrease in tumor volume." (PMID 41009025, 2025). "APS enhanced the antioxidant capacity of tumor-bearing mice, specifically, APS reduced the levels of malondialdehyde (MDA), nitric oxide (NO), and myeloperoxidase (MPO), while increasing the activities of SOD, CAT, and GSH-Px by establishing a mouse ascites tumor model." (PMID 40143189, 2025). "The control and non-tumor treatment groups (Control/GSO, Control/GSONE) clustered together, characterized by elevated antioxidant enzyme activities (SOD, CAT, GSHP-x, GSH), albumin (ALB), and total protein (TP), alongside lower levels of pro-apoptotic and oxidative stress markers." (PMID 41228521, 2025). "Higher T2 signals were observed in deeper tumor tissues following peritumoral injection of FeO@mSiO2/Au-CAT Janus nanomotors, as opposed to passive FeO@mSiO2 nanoparticles, indicating that JNCRs mediated deeper tumor penetration." (PMID 40936648, 2025). "In conclusion, HSA/CAT-PEPA effectively reverses hypoxia, increases ROS generation and improves the efficacy of photodynamic therapy, both in vitro and in vivo, leading to significant inhibition of tumor growth and improved oxygen saturation." (PMID 40286175, 2025). "Recently, a T4-Ce6-catalase (Cat)-lactate oxidase (Lox) (TCCL) biomimetic peroxisome was developed using T4 phage display technology for enhanced PDT, achieving high ROS generation efficiency and tumor inhibition rates, with low immunogenicity." (PMID 40428088, 2025). "Besides, it had a 76% reduction in tumor volume, significantly increased the antioxidant activity (SOD, CAT, GSH), decreased the levels of inflammatory biomarkers (IL-6, COX-2, NF-κB), and markedly downregulated the EGFR expression (p < 0.0001)." (PMID 41599143, 2025). "In cancer, FGF2 promotes tumor angiogenesis and cell proliferation, while under oxidative stress conditions, it enhances the cellular antioxidant defense by upregulating the expression of antioxidant enzymes (SOD, CAT, and GSH-Px) and maintaining GSH levels." (PMID 40363725, 2025). "However, in the GSE32879 dataset, only seven genes (APOA2, CAT, ACOX1, APOE4, AGXT, EHHADH, HSD17B4) were observed to be significantly reduced in tumor samples." (PMID 38274331, 2024).